NTN1 (netrin 1)
Diseases named in the same sentence as NTN1 in open-access papers (continued):
Sharing a sentence is not in itself a finding about the gene and the disease.
lymphoma (1 paper, 2022). A malignant (clonal) proliferation of B- lymphocytes or T- lymphocytes which involves the lymph nodes, bone marrow and/or extranodal sites. "This gain of netrin activity is proven to be a selective advantage for tumor cells survival, both in vitro and in vivo, by using compounds inhibiting/interfering with netrin-1/receptors interactions, especially in some human lymphomas." (PMID 36136711, 2022). "In cells from canine lymphomas, this type of post-transduction alterations in netrin-1 can be considered, redirecting this protein in the cytoplasm of cells, thus inhibiting pro-apoptotic proteins." (PMID 36136711, 2022). "Together, these data suggest that netrin-1 expression is increased in lymphoma, and more specifically in high-grade lymphomas, and that netrin-1 can act as a survival factor for the neoplastic cells, and so be a therapeutic target." (PMID 36136711, 2022). "A T-cell aggressive canine lymphoma cell line and four primary canine nodal lymphomas cell cultures were treated with a netrin-1 interfering antibody." (PMID 36136711, 2022). "The present study examined the expression of netrin-1 in normal canine lymphoid tissues and tissues with nodal lymphoma through immunohistochemistry, flow cytometry, and RT-qPCR." (PMID 36136711, 2022). "Netrin-1 was expressed in all cases, both lymphomas and controls." (PMID 36136711, 2022). "Netrin-1 appears thus as a possible survival factor in dog lymphomas." (PMID 36136711, 2022). "Both in B-cell type and T-cell type, netrin-1 expression was increased in high-grade lymphomas." (PMID 36136711, 2022). "The aim of the present study was to investigate the expression of netrin-1, the ligand of dependence receptors, in canine healthy lymph nodes (LN), and in lymphomas and to evaluate efficiency of a netrin-1 interfering compound in cell cultures from canine lymphoma." (PMID 36136711, 2022). "Therefore, blocking netrin-1 seems a promising way in the therapeutic perspectives of such lymphomas." (PMID 36136711, 2022). "In dogs, immunohistochemistry exhibited that normal lymphoid cells may express netrin-1 but only at a nucleolar level whereas nodal lymphomas cells may also express netrin-1 at a cytoplasmic level." (PMID 36136711, 2022). "We observed increased expression of netrin-1, particularly in high-grade nodal lymphomas." (PMID 36136711, 2022). "Netrin-1 expression can thus be considered as a marker of aggressiveness in canine lymphomas." (PMID 36136711, 2022).
macular edema (1 paper, 2025). "Dysregulation of Netrin-1 expression in human patients with DR was shown to contribute to vascular leak and macular edema." (PMID 41196411, 2025).
memory impairment (1 paper, 2023). "Another evidence in mice showed netrin-1 potential to recover amyloid-β induced memory impairment, during late-phase of Long-Term Potentiation, a process by which synaptic connections between neurons become stronger with frequent activation." (PMID 37307281, 2023).
meningioma (1 paper, 2024). A generally slow growing tumor attached to the dura mater. "Plasma or serum netrin-1 levels are significantly increased in lung, breast, prostate, colorectal, renal, liver, meningioma, pituitary adenoma, and glioblastoma cancers." (PMID 38638604, 2024). "In a large scale of clinical blood samples from cancer patients, plasma Netrin-1 levels are significantly higher in breast, renal, prostate, liver, meningioma, pituitary adenoma, and glioblastoma cancers than it in controls." (PMID 38638604, 2024).
metastasis (1 paper, 2023). The spread or migration of cancer cells from one part of the body (where they first appeared) to another. "This study proves that PLAC1 and Netrin-1 are related to the degree of differentiation and lymph node metastasis of CRC liver metastasis, and can better judge the possibility of liver metastasis, which has certain clinical research value." (PMID 37568074, 2023).
monocytic leukemia (1 paper, 2022). "In vitro studies in human visceral adipocytes and human monocytic leukemia cells (THP-1)-derived macrophages were performed to analyze the impact of inflammation-related mediators on the gene expression levels of NTN1 and its receptor NEO1 as well as the effect of NTN-1 on inflammation." (PMID 36297056, 2022).
mood disorder (1 paper, 2021). A cognitive disorder a disturbance in which the person's mood is hypothesized to be the main underlying feature. "An important question is whether the sensitivity of the Netrin-1/DCC pathway is also sex-specific, considering sex-differences in adolescent brain development, prevalence of mood disorders and impulsivity." (PMID 33619036, 2021).
osteosarcoma (1 paper, 2023). A usually aggressive malignant bone-forming mesenchymal neoplasm, predominantly affecting adolescents and young adults. "CDK8, EEF1A1, and NTN1 have been confirmed as direct target genes of miR-PC-2869 in osteosarcoma cells, and their involvement in the pathogenesis of various human cancers has been previously reported." (PMID 37446017, 2023). "Thus, we hypothesized that CDK8, EEF1A1, and NTN1 mediate the tumor-suppressor activity of miR-PC-2869 in osteosarcoma cells." (PMID 37446017, 2023).
ovarian tumours (1 paper, 2013). "Moreover, we have shown using a panel of human samples that primary ovarian tumours from patients treated with Carboplatin/Taxol displays an increase in netrin-1 level compared to the same tumours before treatment." (PMID 24293316, 2013).
paraganglioma (1 paper, 2025). A benign or malignant neoplasm arising from paraganglia located along the sympathetic or parasympathetic nerves. "Only one case of NTN1 and its receptor mutation was found in pheochromocytoma, paraganglioma, and uveal melanoma." (PMID 41407823, 2025).
periodontal disease (1 paper, 2022). "To the best of our knowledge, we are among the first to test the role of netrin-1 in periodontal disease and health." (PMID 35919444, 2022). "The current study tested netrin-1 as a reliable inflammatory marker of periodontal disease." (PMID 35919444, 2022). "Based on these findings, we suggest that netrin-1 could be considered a potential anti-inflammatory biomarker of periodontal disease." (PMID 35919444, 2022).
periodontitis (1 paper, 2022). An acute or chronic inflammatory process that affects the tissues that surround and support the teeth. "Six weeks after SRP, there was a significant increase in GCF netrin-1 level in periodontitis patients, although it was significantly lower than the control value." (PMID 35919444, 2022). "Netrin-1 GCF levels were significantly lower in periodontitis patients than periodontally healthy individuals at baseline with a significant increase in netrin-1 GCF levels after SRP (P<0.05)." (PMID 35919444, 2022). "GCF netrin-1 levels were markedly lower in periodontitis patients than in healthy ones in the present study." (PMID 35919444, 2022). "Estimation of netrin-1 GCF level showed significantly lower levels in periodontitis patients than periodontally healthy individuals." (PMID 35919444, 2022). "The present study was undertaken to investigate the impact of periodontitis and SRP on GCF netrin-1 levels, testing it as a novel and reliable periodontal inflammatory marker." (PMID 35919444, 2022).
peripheral artery disease (1 paper, 2020). "In addition, we believe that Netrin-1 is a candidate marker for further study in thrombotic-ischemic events, such as cerebrovascular events, peripheral artery disease, pulmonary embolism, and mesenteric ischemia, wherein angiogenesis increases." (PMID 32455061, 2020).
polyneuropathy (1 paper, 2021). A disease or disorder affecting more than one nerve. "In skin samples of patients with polyneuropathy, NTN1 in proximal and DCC and NEO1 (two attracting receptors) in distal specimens are reduced." (PMID 34576252, 2021).
proliferative diabetic retinopathy (1 paper, 2023). Advanced retinopathy due to diabetes mellitus characterized by the formation of new vessels in the retina. "Lastly, Netrin-1 and CD146 expression is significantly increased in the proliferative retinal tissues of human proliferative diabetic retinopathy patients." (PMID 37153740, 2023).
prostate adenocarcinoma (1 paper, 2025). "NTN1 only predicted the NTN1-RANGAP1 and NEO1 fusion gene in endocrine-associated cancer (OV, BRCA, and prostate adenocarcinoma [PRAD]) in UCEC." (PMID 41407823, 2025).
psoriasis (1 paper, 2022). An autoimmune condition characterized by red, well-delineated plaques with silvery scales that are usually on the extensor surfaces and scalp. "Through comprehensive bioinformatic analysis, this study identified DEGs normal in psoriasis; that is, gathering in DNA replication, cell cycle, DCC-intervened pathways, and Netrin-1 flagging pathways." (PMID 36499614, 2022).
pulmonary edema (1 paper, 2010). Accumulation of fluid in the lung tissues causing disturbance of the gas exchange that may lead to respiratory failure. "We found reduced signs of pulmonary edema, patchy infiltrates and inflammatory changes in the animals treated with netrin-1 i.v. or netrin-1 inh." (PMID 20969752, 2010).
rectal tumors (1 paper, 2023). "However, in rectal tumors or inflammatory diseases, NTN1 expression is restored, leading to disease progression." (PMID 37345154, 2023).
renal carcinoma (1 paper, 2025). A carcinoma arising from the epithelium of the renal parenchyma or the renal pelvis. "In general, NTN1, NEO1, DSCAM, UNC5C, and UNC5D are all regulated by HDAC members in renal cancer, suggesting that NTN1, NEO1, DSCAM, UNC5C, UNC5D, and especially NEO1 and UNC5C may be essential for the regulation and outcome of renal cancer." (PMID 41407823, 2025).
renal clear cell carcinoma (1 paper, 2025). "For example, for renal clear cell carcinoma driven by UNC5D methylation, a combination protocol of “HDAC inhibitor (restoring UNC5D expression) + netrin-1 antibody” can be explored to simultaneously inhibit tumor proliferation and immune evasion." (PMID 41407823, 2025).
renal hypoplasia (1 paper, 2023). Renal hypoplasia is a developmental anomaly in which one or both kidneys (unilateral or bilateral renal hypoplasia, respectively) have a deficit in the number of nephrons and may be small. "It is possible that loss of Ntn1 results in increases in Bmp4 and a subsequent reduction in Gdnf activity, leading to renal hypoplasia." (PMID 37131589, 2023).
rotator cuff tear (1 paper, 2025). "Supraspinatus tendon analysis demonstrated a coordinated, time-dependent induction of netrin-1 signaling components after rotator cuff tear." (PMID 40728980, 2025). "Netrin-1 and its receptors are upregulated in a rat rotator cuff tear model, and netrin-1 elicits distinct pro-inflammatory and matrix-remodeling responses in tenocytes while promoting early neurite growth in sensory neurons." (PMID 40728980, 2025). "By illuminating this novel signaling axis, our findings lay the groundwork for future studies to explore targeted modulation of netrin-1 pathways as a strategy to mitigate pain and improve healing after rotator cuff tears." (PMID 40728980, 2025). "In this study, we demonstrate for the first time that netrin-1 and its dependence receptors UNC5B and Neogenin-1 are coordinately upregulated in a rat rotator cuff tear model, with peak expression in the subacute phase of tendon injury." (PMID 40728980, 2025). "By integrating these in vivo and in vitro approaches, we aim to elucidate the mechanistic role of netrin-1 signaling in tendon inflammation, matrix remodeling, and nociceptive sensitization following rotator cuff tears." (PMID 40728980, 2025).
schwannoma (1 paper, 2017). A benign, usually encapsulated slow growing tumor composed of Schwann cells. "Knockdown Unc5B in RT4 schwannoma cell using Unc5B specific RNAi significantly reduced Netrin-1 induced RT4 schwannoma cell proliferation." (PMID 28245592, 2017). "Netrin-1 treatment (50 ng/mL) induced RT4 schwannoma cell proliferation." (PMID 28245592, 2017).
skin cancer (1 paper, 2023). "In our study, the expression of NTN1 was significantly positively correlated with mast cells, which modulated the cutaneous inflammatory reactions and acted as potential players in different types of skin cancers including SKCM." (PMID 37404751, 2023).
T-cell lymphomas (1 paper, 2022). "In canine T-cell lymphomas, an increased netrin-1 cytoplasmic expression in high-grade subtypes was present, especially in aggressive large granular T-cell lymphomas, a subtype with poor prognosis." (PMID 36136711, 2022). "In vitro evaluation of an anti-netrin-1 antibody is encouraging as apoptosis is restored in a T-cell lymphoma cell line." (PMID 36136711, 2022). "No data have been published about humans regarding expression of netrin-1 in T-cell lymphomas." (PMID 36136711, 2022). "In T-cell nodal lymphomas, netrin-1 nucleolar expression was present in 64.3% of low-grade T-cell lymphomas and in 56.2% of high-grade T-cell lymphomas; this difference of netrin-1 nucleolar expression between low- and high-grade T-cell lymphomas was not significant (p = 0.91)." (PMID 36136711, 2022). "An increase in cytoplasmic expression of netrin-1 in high-grade (78.8% of cases were positive) compared with low-grade (50.0% of cases were positive) T-cell lymphomas was present although not significant (p = 0.052)." (PMID 36136711, 2022).
temporomandibular joint disorder (1 paper, 2021). Any condition affecting the anatomic and functional characteristics of the temporomandibular joint. "The synovial fluids of temporomandibular joint disorders (TMDs) patients were collected for Netrin-1 by enzyme linked immunosorbent assay (ELISA)." (PMID 34344989, 2021).
testicular germ cell tumor (1 paper, 2020). A germ cell tumor arising from the testis. "The expression of NTN1 and NTN4 was related to radiation therapy and pathologic stage in Testicular Germ Cell Tumors (TGCT)." (PMID 32251318, 2020).
thymic carcinoma (1 paper, 2020). Thymic carcinoma (TC) is a type of thymic epithelial neoplasm characterized by a high malignant potential. "We found that half of the mirRNA in thymic carcinoma had a strong inhibitory effect on NTN1." (PMID 32251318, 2020).
thyroid cancer (1 paper, 2020). "Thus, these eQTLs may alter the activity of these transcription factors to generally promote NTN1 transcription, resulting in thyroid cancer." (PMID 32251318, 2020). "Additionally, high expression of NTN1 in thyroid carcinoma was correlated with a worse survival." (PMID 32251318, 2020). "The transcription of NTN1 and NTNG2 is positively regulated by MYC in THCA, suggesting that NTN1 and NTNG2 may also participate in the development of thyroid carcinoma." (PMID 32251318, 2020).
thyroid dysgenesis (1 paper, 2025). "However, additional evidence is needed to determine the role of NTN1 mutations in thyroid dysgenesis." (PMID 41303336, 2025). "In a cohort of 161 unrelated patients with thyroid dysgenesis, one patient with thyroid ectopia and a ventral septal defect was diagnosed with NTN1 deletion." (PMID 41303336, 2025).
transient cerebral ischemia (1 paper, 2018). "Furthermore, DCC is expressed in both neurons and astrocytic feet and affects the promoting effects of Netrin-1 on axonal growth after a transient cerebral ischemia." (PMID 29487502, 2018).
cancer (102 papers, 2005 to 2025). A tumor composed of atypical neoplastic, often pleomorphic cells that invade other tissues. "The gene encoding DCC is frequently deleted in cancer, and Netrin-1 blocking antibodies are in Phase II clinical trials for endometrial and cervical carcinomas to inhibit metastatic growth." (PMID 39023520, 2024). "The higher expression of netrin-1 was also found in CAFs and associated with the increasing stemness in cancer cells, thereby mediating drug resistance." (PMID 37065872, 2023). "And the functional differences of netrin-1 in malignant tumors suggested that the functions and underlying mechanisms of netrin-1 were diverse and complex." (PMID 35974411, 2022). "Other significantly over-expressed genes in radioresistant PDOs – namely PLK2, UBASH3B, and NTN1 – have been associated with cancer progression." (PMID 35860583, 2022). "There is irrefutable proof in animal models of cancer that silencing NTN1 with small interfering RNA is associated with inducing cell apoptosis." (PMID 30923634, 2019). "Although netrin-1 has been implicated in cancer cell survival and cell motility, there is little research regarding its role in cancer cell proliferation." (PMID 28710382, 2017). "The involvement of Netrin-1 in hepatic pathobiology and the role of DR ligands in the persistence of infectious agents associated with cancer deserve further investigation." (PMID 27031829, 2016). "Accordingly, Netrin-1, a reprogramming modulator, is upregulated in several cancer types as well as in cancer-associated inflammatory diseases such as colitis and Crohn’s disease —for review, see Paradisi and Mehlen." (PMID 27031829, 2016). "This functional association involving a cancer-related virus and Netrin-1 argues for evaluating the implication of UNC5 receptor ligands in other oncogenic microbial species." (PMID 27031829, 2016). "The truncated ΔN-netrin-1 variant which localizes to the nucleolus has been shown to affect ribosome biogenesis resulting in cancer cell proliferation." (PMID 24647424, 2014). "Similarly, in cancer models, netrin-1 has been implicated in tumor progression and metastasis, potentially by protecting cells from apoptosis and modulating the tumor microenvironment." (PMID 40728980, 2025). "Interestingly, it has also been shown that netrin-1 is elevated in cancer-associated fibroblasts (CAFs) in addition to cancer cells." (PMID 36499024, 2022). "Importantly, NTN1 recently is upregulated in cancer-associated fibroblasts, modulating tumor plasticity." (PMID 33724150, 2021). "Ramesh G, Berg A, Jayakumar C. Plasma netrin-1 is a diagnostic biomarker of human cancers." (PMID 32267322, 2020). "The axon guidance indicates that netrin 1 and Slits are causally involved in human cancer." (PMID 30881993, 2019). "In some cancers a truncated form of NTN1 is detected and associates with poor patient survival." (PMID 30923634, 2019). "Although previous studies have implicated that NTN1 may regulate cancer cell invasion this is the first time a connection to cancer stem cells is described." (PMID 28069038, 2017). "Interestingly, many cancer samples showed a strong nuclear netrin-1 signal which was recently linked to a truncated netrin-1 variant that enhances tumor growth." (PMID 24647424, 2014). "Netrin-1 is an early diagnostic biomarker of acute kidney injury and cancers." (PMID 22046354, 2011). "Thus, like netrin-1, unc5b might exert different functions in different malignant tumors, and the underlying mechanism needs further investigation." (PMID 35974411, 2022).